CD44 (CD44 molecule (IN blood group))
Diseases named in the same sentence as CD44 in open-access papers (continued):
Sharing a sentence is not in itself a finding about the gene and the disease.
cancer (continued). "PDX models transduced with a reporter to enable tracking of cells have indicated that CD44+ breast tumor cells enriched for cancer stem cells spontaneously metastasize to the lungs and lymph nodes, thus suggesting a role for cancer stem cells in primary tumor growth as well as metastatic spread." (PMID 25849559, 2015). "The question remains whether other molecular functions of CD44 drive its involvement in specific types of cancers." (PMID 25904917, 2015). "CD44 is a major cell adhesion molecule that participates in various physiological events, including lymphocyte homing, wound healing, and cell migration as well as in cancer cell growth and metastasis." (PMID 25331984, 2015). "CD44 thus maintains a key role in the GSH-dependent antioxidant system in cancer cells." (PMID 26273420, 2015). "First, we tested cancer stem cell surface marker CD44 by immunofluorescence." (PMID 26498753, 2015). "Furthermore, we have demonstrated that the ability of FKBPL to bind CD44 makes it useful for targeting cancer stem cells (CSCs), which express high levels of CD44." (PMID 25906750, 2015). "Our findings provide an alternative mechanism of cancer resistance to lestaurtinib and indicate that dual inhibition of CD44 and TrkA tyrosine kinase activity may represent a novel therapeutic strategy." (PMID 25840418, 2015). "Analysis of genes that are coexpressed with CDH1 (E-cadherin) in microarrays across 917 different cell lines from the cancer cell line encyclopedia demonstrates that the CD44 splicing protein, ESRP1, is one of the most highly correlated genes with CDH1 expression." (PMID 25850653, 2015). "In addition, HA has been used as an active ligand for targeted cancer therapy since its receptor CD44 (cluster of differentiation 44) has been found to be overexpressed in various cancers." (PMID 27182458, 2015). "CD44 plays a role in the progression of tumors and is expressed in cancer stem cells (CSCs)." (PMID 25909162, 2015). "The smallest form of CD44, designated standard CD44 (CD44s), is abundantly expressed in both normal and cancer cells, whereas the CD44v, which contain a variable number of exon insertions (v1–v10), are mostly expressed in cancer cells." (PMID 25909162, 2015). "This evidence suggests that the CD44/OCT4-expressing cancer cells in the NPC sections were CSCs." (PMID 26202311, 2015). "We were also interested in the effect of autophagic inhibition on reported virulent transformation markers, such as CXCR4, SOX9, and CD44, and on chemokines, such as CXCL1 and IL8, since various reports have indicated that these markers and inflammation are associated with cancer initiation." (PMID 26496833, 2015). "Indeed, increasing evidence points to a role for CD44 as a critical mediator of both growth factor- and HA-induced invasive signaling in cancer cells." (PMID 26005723, 2015). "In addition to hyaluronan, CD44’s interaction with certain growth factors also plays important roles in cancer progression." (PMID 26347743, 2015). "Other studies have shown that CD44-positive cancer cells up-regulate antioxidant genes." (PMID 26322272, 2015). "We summarized the data and concluded that activation of TGFβ signaling induced by ADT led to de-differentiation phenotype as a result of increased CD44+ cancer stem like cell population, which subsequently generated to EMT like cell through TGFβ/CD44 signaling." (PMID 25483103, 2015). "CD44 is a heterogeneous, transmembrane glycoprotein which is overexpressed on the surface of cancer stem cells and plays a crucial role in the development of different types of cancer." (PMID 26113878, 2015). "Together, cancer stem-like (CD44+) cells could be the initiator cells of EMT modulated by TGFβ1-CD44 signaling." (PMID 25483103, 2015).
cancer (continued). "Upon conjugation to HA, water solubility of the prodrug HA-PTX, and of HYTAD1-p20 (a HA-PTX conjugate renamed as ONCOFID-P by the pharmaceutical company Fidia) significantly increased CD44 dependent cellular uptake in vitro and in vivo in cancer cells, including bladder carcinoma cells." (PMID 25999946, 2015). "The well-accepted cancer stem cell surface markers are CD44, CD24, CD133, CD166, EpCAM." (PMID 26513297, 2015). "We also speculate that by targeting P-gp-positive/CD44-positive cancer cells, we will be aiming at cancer stem cells that are slow growing and more difficult to kill with standard cytotoxic agents." (PMID 26299618, 2015). "Altogether, our findings provide an alternative mechanism of cancer resistance to lestaurtinib and indicate that dual inhibition of CD44 and TrkA tyrosine kinase activity may represent a novel therapeutic strategy." (PMID 25840418, 2015). "Anti-CD44 antibodies have also been evaluated as an anti-cancer therapeutic." (PMID 25954275, 2015). "Many of the contradictory findings published to date may be due to experimental and technical differences among studies; however, a picture has emerged suggesting that CD44 may function differently at different stages of cancer progression." (PMID 26448753, 2015). "However, when stratified according to histology, AC displaying the putative cancer stem cell (CSC) signature CD24−/CD44+ had a significantly shorter overall survival than CD24+/CD44− AC." (PMID 26578846, 2015). "We found that silencing CD44 inhibited cancer cell proliferation." (PMID 25605020, 2015). "Similarly, changes in expression patterns were detected in normal cells and cancer cells by western blotting using an immunoblotting antibody against the standard region of CD44." (PMID 25909172, 2015). "In such cases, examining markers for proliferation, such as Ki-67, or cancer stem cell markers, such as CD44, may elucidate potential intratumoral effects." (PMID 25642322, 2015). "Targeting hyaluronan–CD44 axis is one of the principal ways, and the lipid raft-targeted delivery of hyaluronan-grafted liposomes could have important applications in cancer therapy." (PMID 26347743, 2015). "CD44 - an important regulator of HA-mediated signaling in cancer?" (PMID 26029216, 2015). "CD44 is a known HA receptor and prominent marker of CSCs in several types of cancer." (PMID 26322272, 2015). "However, the HA-binding abilities of CD44 were significantly higher for cancer tissues compared with normal tissues, strongly suggesting that a discordant relationship of CD44 expression and activation exists between cancerous and normal breast tissues." (PMID 25909172, 2015). "Immunodetection of cells with CD44+/CD24− phenotype in canine mammary tumor tissues, similarly to human BC CSCs, has been also reported, and CD44 expression has been associated with proliferation of cultured canine cancer cells." (PMID 25884842, 2015). "This kind of CD44+ cancer stem like cell could be as an initiator of EMT like cell with the function of metastasis." (PMID 25483103, 2015). "CD44 has been found expressed in embryonic, hematopoietic, epithelial, and cancer stem cells." (PMID 26064420, 2015). "However, many lines of evidence indicate that CD44 organizes a signaling platform by which cancer cells survive and grow in addition to seeding metastases." (PMID 26569327, 2015). "All of these findings highlight the important roles of CD44 in cancer progression and recurrence." (PMID 26322272, 2015). "Cancer-associated fibroblasts generated from CD44 knockout mice did not result in a sustained CSC state." (PMID 25954275, 2015). "The HA-LIP conjugate can be used to deliver plasmid DNA and siRNA to CD44 positive cancer cells." (PMID 26448753, 2015). "Similar dual functions of CD44 exist in initiation and progression of cancer." (PMID 25999946, 2015). "However, the correlation of CD44 expression levels with cancer prognosis and the utility of CD44 as a CSC marker are debatable." (PMID 25909162, 2015).
cancer (continued). "CD44-expressing cancer cells can acquire the capability to evade immune destruction." (PMID 26322272, 2015). "Therefore, we focused our attention on two related RNA binding proteins, IGF2BP1 and IGF2BP3, which bind and control CD44 mRNA stability in several cellular system and their expression is tightly related to CD44 levels in several forms of cancer." (PMID 26429859, 2015). "In conclusion, therefore, we speculate that pharmacological targeting of CD44 palmitoylation may offer a fresh strategy to reduce cancer cell dissemination during the early stages of metastasis." (PMID 24512624, 2014). "Besides CD44, a number of CD markers have been identified as cancer stem cell markers in several solid tumors." (PMID 24122205, 2014). "Furthermore, since serum-starved conditions have been shown to increase the amount of CD44-positive cancer stem-like cells, we wanted to elucidate if this increase was also true for any of the CD44 splice variants." (PMID 24122205, 2014). "Since adhesion to endothelial cells is a first crucial rate-limiting step of hematogenous CRC liver metastasis after intrasplenic injection and the CD44 receptor is known to regulate cancer cells adhesion, we next evaluated role of CD44 on CRC metastasis invivo." (PMID 24823486, 2014). "This kind of conjugate can be used to deliver plasmid DNA and siRNA to CD44 + cancer cells." (PMID 24642908, 2014). "Furthermore, several studies describe CD44 to be a cancer stem cell marker for various malignancies." (PMID 24122205, 2014). "This would suggest that the use of an AKT inhibitor could indeed increase the radiation sensitivity but may instead induce CD44 expressing cancer cells." (PMID 24760019, 2014). "These cells, termed induced cancer stem cell-like 10A (iCSCL-10A), express cancer stem markers (CD44, CD133 and ALDH1) and show much higher sphere forming ability than conventional cancer cell lines even in regular cell culture media supplemented with fetal bovine serum." (PMID 25228591, 2014). "In addition, CD133/CD44 highly expressing populations of cancer cells have been shown to be invasive in vitro and are responsible for metastases in vivo in mice." (PMID 24760019, 2014). "Cisplatin-based chemotherapy induced demethylation of miR-34a promoter and increased miR-34a expression, which in turn sensitized MIBC cells to cisplatin and decreased the tumorigenicity and proliferation of cancer cells that by reducing the production of CD44." (PMID 24423412, 2014). "Up-regulation of CD44 has been shown to increase proliferation and invasiveness of cancer cells." (PMID 25184276, 2014). "Interestingly, co-expression of CD133+ and CD44+ with high ALDH activity identified an enriched CSC-like population within established cancer cell lines." (PMID 25228591, 2014). "Previous studies have proposed that it is not the mutation of CD44 but those factors promoting carcinogenesis that control the patterns of the misregulated CD44 in most cancers." (PMID 24971320, 2014). "CD44 is a member of the cell adhesion protein family and the expression of several CD44 proteins has been found to correlate with aggressive stages of various types of human cancer." (PMID 24932297, 2014). "The metastatic cancer cells were shown by IHC to express human CD44." (PMID 24713276, 2014). "Therefore determining the exact function that CD44 plays in each cancer cell line becomes increasingly important for the utilization of CD44 as a therapeutic target." (PMID 24823486, 2014). "Increased levels of hyaluronan and CD44 could also stimulate cell proliferation and migration as found in cancer malignancy." (PMID 25309501, 2014). "CD44 was initially identified as a lymphocyte homing receptor and transmembrane glycoprotein commonly expressed in embryonic stem cells and in hematopoietic and cancer stem cells." (PMID 24708709, 2014). "The variety of dominant CD44 isoforms expressed in different cancers might be responsible for this phenomenon." (PMID 24971320, 2014).
cancer (continued). "Finally, the metastatic BC cells in the hTEBCs expressed human CD44, an adhesion receptor for the extracellular matrix proteins hyaluronan and osteopontin, which is known to promote cancer cell migration, invasion and metastasis." (PMID 24713276, 2014). "It has a widely recognized tumour promoting role in several cancer types such as prostate, ovarian and breast cancers via activating e.g., CD44 and RHAMM (receptor for hyaluronan-mediated motility) mediated signaling pathways including NFκB and mitogen-activated protein kinase (MAPK) pathways." (PMID 26056582, 2014). "CD44 has also been identified as one of the CSC markers in various other cancer types." (PMID 24612587, 2014). "In fact, CD44 is considered to be one of the important surface markers on cancer stem cells." (PMID 24606718, 2014). "CD44 is one of the most frequently observed cancer stem cell (CSC) markers in solid tumors, and it was revealed to be a target of the Wnt pathway, which is accepted as a main pathway for the stemness maintenance of CSCs, and usually accepted as a poor prognosis marker." (PMID 24410905, 2014). "Significantly, CD44+/CD24−/Low CSCs displayed a higher resistance to methotrexate while they where highly sensitive to the Cdk2 inhibitor SU9516 compared to bulk SUM149PT cancer cells." (PMID 24970653, 2014). "Recently, CD44 was shown to be a cancer stem cell marker, and it was reported that CD44 could promote cell motility and tumorigenicity." (PMID 25304388, 2014). "We also analyzed the expression of the putative cancer stem cell (CSC) marker CD44." (PMID 25373388, 2014). "In addition, Galectin-1 mediated attachment of cancer cells to the extracellular matrix and endothelial cells through binding to CD44 and CD326 on murine breast and colon cancer cells." (PMID 24592356, 2014). "Moreover, we established that only SUM149PT cancer cells contain a CD44+/CD24−/Low CSCs subpopulation displaying centrosome amplification that was functionally linked to cyclin E overexpression and Rb phosphorylation." (PMID 24970653, 2014). "The discovery of CD44+/CD24low/− CSCs has generated excitement because this subpopulation of cancer cells may represent a source of therapeutic failure to anticancer drugs." (PMID 24970653, 2014). "Taken together, this might suggest that, in the early stages of cancer progression, the standard form of CD44 becomes prevalent and localises outside lipid rafts in order to bind its oncogenic binding partners and stimulate cell migration." (PMID 24512624, 2014). "Moreover, several reports have described prognostic power of CD44 gene products in different cancer types." (PMID 23565227, 2013). "To determine whether PGCCs have increased levels of cancer stem cell markers, we examined the expression pattern of the cancer stem cell-related markers CD44, Nanog, and OCT3/4 in these cells." (PMID 24348907, 2013). "CD44 is a CSC marker known to be involved in cancer cell adhesion and migration." (PMID 24423398, 2013). "CD44 has been identified as a specific marker of cancer stem cells." (PMID 23706092, 2013). "We hypothesized that CD44 might contribute to the cancer stem cell traits by regulating pSTAT3 and hTERT in the integrated signal pathway." (PMID 24386318, 2013). "As CD44 antigen have shown a correlation with chemoresistance, the presence of cancer stem cells expressing CD44 may contribute to the acquisition of growth potential as well as drug resistance." (PMID 24039920, 2013). "This inhibitor has been used to inhibit CD44 cleavage in several types of cancer." (PMID 24403253, 2013). "In addition, as a class I transmembrane glycoprotein, CD44 was highly expressed not only in cancer cells but also in immune cells (such as leukocytes) and stromal cells (such as fibroblasts)." (PMID 23710217, 2013). "CD44 is considered the surface marker of a variety of cancers." (PMID 23803658, 2013).
cancer (continued). "Thus, it has been shown for many cancer types that the tumorigenic cells expressing common CSC markers, in particular CD133 and CD44, are exceptionally resistant to conventional anti-cancer drugs (such as 5-FU, oxaliplatin, irinotecan, docetaxel and others)." (PMID 24086245, 2013). "CD44 is also involved in the regulation of the glycolytic pathway by modulating cellular reduced glutathione and contributes to antioxidant status and drug resistance in cancer cells." (PMID 23803658, 2013). "CD44, a multifunctional class I transmembrane glycoprotein, generally acts as a specific receptor for hyaluronic acid, promoting migration in normal cells and is highly expressed in almost every cancer cell." (PMID 23401782, 2013). "The CD44/CD24 immunophenotypes behavior shows great diversity in human cancers." (PMID 23419168, 2013). "Finally, CD44 knock-down resulted in the abrogation of cancer stem cell phenotype and concurrent down-regulation of pSTAT3 and hTERT." (PMID 24386318, 2013). "Alternative splicing of CD44 variant exons generates a great many isoforms, and it is not known which isoforms are expressed on the surface of the two different cancer stem-like cell phenotypes." (PMID 23437366, 2013). "Given that circulating CD45-CD90+CD44+ cells detected by flow cytometry were associated with early HCC recurrence, circulating cancer stem cell markers may have significant prognostic values in HCC." (PMID 24244607, 2013). "Therefore, CD44-targeted MR imaging has been applied in the treatment of cancer such as monitoring therapeutic efficacy and determining the progonosis of cancer." (PMID 23547716, 2013). "CD44 is also a biomarker of breast cancer tumor propagating cancer stem cells (CSCs); chemotherapy resistant cells with metastatic activity capable of forming other cancer cell populations." (PMID 23295955, 2013). "Furthermore, CD44+ cancer cells are considered to be slow-cycling, therefore insensitive to chemoradiotherapies." (PMID 23833643, 2013). "CD44 is considered a potential CSC marker in majority of cancers." (PMID 22693526, 2012). "All markers identifying cancer stem cells are surface markers such as epithelial cell adhesion molecule (EpCAM), CD44, CD24, CD133 and C-X-C chemokine receptor type 4 (CXCR4) definitely expressed on the normal stem cells at the same time and apparently changing during cancer stem cell development." (PMID 22452810, 2012). "In addition, CD44, a cancer stem-like cell marker, inversely correlated with increased cell surface MT1-MMP." (PMID 22679501, 2012). "However, the influence of alteration in CD44 function on normal stem cells has to be considered during experiments on a cancer patient." (PMID 22693526, 2012). "Indeed, increasing evidence points to a role for CD44 as critical mediators of both growth factor- and HA-induced mitogenic and invasive signalling in cancer cells." (PMID 23039365, 2012). "However, CD44 is expressed in almost all cancers, likewise, recent reports show CD24 is also enriched in ovarian CSCs." (PMID 22693526, 2012). "CD24 has been investigated in combination with CD44 and other markers in various cancers." (PMID 22693526, 2012). "The majority of cancer cell lines express high levels of CD44." (PMID 22693526, 2012).